IL37 (interleukin 37)
Description:
Immune regulatory cytokine that acts as a suppressor of innate inflammatory and immune responses involved in curbing excessive inflammation. Signaling can occur via two mechanisms, intracellularly through nuclear translocation with SMAD3 and extracellularly after secretion and binding to its receptor composed of IL18R1 and IL18RAP. Suppresses, or reduces, pro-inflammatory cytokine production, including IL1A and IL6, as well as CCL12, CSF1, CSF2, CXCL13, IL1B, IL23A and IL1RN, but spares anti-inflammatory cytokines. Inhibits dendritic cell activation.
Synonyms: IL-37; IL-1F7; IL-1H; IL-1H4; IL-1RP1; FIL1Z; IL1F7; IL1H4; IL1RP1; FIL1; FIL1(ZETA); IL-23
Tractability: Antibody: UniProt places it where antibodies can reach, with high confidence; its Gene Ontology location is reachable by antibodies, with high confidence.
Gene: Protein-coding gene on chromosome 2 (112,911,165 to 112,918,882, forward strand). Ensembl gene ENSG00000125571.
Subcellular location: Cytoplasm, cytosol; Nucleus; Secreted
Subcellular location (Human Protein Atlas): Cytosol; Nucleoplasm; Vesicles; Predicted to be secreted
Pathways (Reactome):
Immune System: Interleukin-18 signaling; Interleukin-37 signaling
Gene Ontology:
Molecular function: protein binding; cytokine activity; interleukin-1 receptor binding
Biological process: negative regulation of interleukin-6 production; negative regulation of tumor necrosis factor production; regulation of inflammatory response; cellular response to lipopolysaccharide; cytokine-mediated signaling pathway; immune response; inflammatory response; negative regulation of inflammatory response; negative regulation of lipopolysaccharide-mediated signaling pathway; negative regulation of transforming growth factor beta production
Cellular component: cytoplasm; cytosol; extracellular region; nucleoplasm; nucleus; transcription repressor complex
Genetic constraint (gnomAD): Loss-of-function variants: 13 observed, 12.13 expected, observed/expected ratio (o/e) 1.07, 90% interval 0.7 to 1.67. The upper end of that interval is the gene's LOEUF score, 1.67, which puts it in group 6 of 6, group 1 being the genes least tolerant of losing a copy. Missense variants: 242 observed, 242.76 expected, observed/expected ratio (o/e) 1, 90% interval 0.9 to 1.11. Synonymous variants: 89 observed, 92.32 expected, observed/expected ratio (o/e) 0.96, 90% interval 0.81 to 1.15.
Homologues: Orthologues: macaque IL37 (95% identical), dog IL37 (69% identical), zebrafish il1b (22% identical), zebrafish il1fma (19% identical). Paralogues in human: IL36G (25% identical), IL36A (23% identical), IL36RN (22% identical), IL36B (22% identical), IL1F10 (21% identical), IL1RN (20% identical), IL1B (17% identical).
Diseases named in the same sentence as IL37 in open-access papers:
IL37 is named in the same sentence as 324 diseases in open-access papers, as found by Europe PMC text mining. Sharing a sentence is not in itself a finding about the gene and the disease. The quoted sentences say what the papers report.
psoriasis (135 papers, 2012 to 2026). An autoimmune condition characterized by red, well-delineated plaques with silvery scales that are usually on the extensor surfaces and scalp. "Interleukin-37 (IL-37) and Interleukin-38 (IL-38) operate via distinct mechanisms in the pathogenesis of psoriasis, diverging from the pathways associated with previously characterized interleukins." (PMID 40731810, 2025). "IL-37 expression is decreased in psoriasis, and mutations of IL36RN can cause generalised pustular psoriasis." (PMID 35929827, 2022). "Unlike GATA3, the expression of miR-155 significantly increased in the tissues of psoriasis lesions and is negatively associated with IL-37 and GATA3." (PMID 34025671, 2021). "IL-37 also is implicated in the inflammatory process of other disease processes like psoriasis, psoriatic arthritis, atherosclerotic process like lipid metabolism and apoptosis." (PMID 32968566, 2020). "Despite advances in understanding their underlying mechanisms, recent research highlights the significance of interleukins IL-18 and IL-37, in Th1, Th2, and Th17 inflammatory responses, closely associated with the pathogenesis of psoriasis and atopic dermatitis." (PMID 39126010, 2024). "This leads to an imbalance of the IL-33–IL-37 axis, involving increased IL-33 and decreased IL-37, which may be associated with the pathogenesis of AD and psoriasis." (PMID 37834081, 2023). "In addition, the overexpression of IL-37 in HaCaT keratinocytes suppressed the production of proinflammatory cytokines, and the delivery of plasmid encoding IL-37 into keratin 14-VEGF transgenic mice ameliorated the symptoms of psoriasis." (PMID 30918469, 2019). "Therefore, IL-38 and IL-37 are probably also involved in the pathogenic pathways of psoriasis." (PMID 36012744, 2022). "Sequential tape‐stripping adjacent to the psoriasis lesion border shows IL‐37 is highly expressed right at the lesion border and trends downwards as the distance from the lesion increases." (PMID 39157924, 2025). "IL37 in the skin lesions of psoriasis patients mainly originates from activated keratinocytes and neutrophils." (PMID 40060194, 2025). "Additional studies are necessary to delineate the full spectrum of IL-37’s immunomodulatory functions and to evaluate its potential as a therapeutic agent in human psoriasis." (PMID 40731810, 2025). "Both IL-18 and IL-37 have shown abnormal expression levels in various inflammatory and autoimmune disorders, including skin diseases such as atopic dermatitis (AD) and psoriasis." (PMID 39126010, 2024). "Despite there being much ground to cover, accumulating evidence highlights the involvement of IL-18 and IL-37 in the pathogenesis of inflammatory diseases such as AD and psoriasis." (PMID 39126010, 2024). "This review highlights the complex involvement of IL-18 and IL-37 in the immune innate and adaptative systems and their roles in AD and psoriasis." (PMID 39126010, 2024). "In randomized phase 2 trial, cutaneous levels of IL-37 in psoriasis lesions rapidly increased following treatment with tofacitinib." (PMID 39126010, 2024). "Since hBDs, including hBD-3, are over-expressed in the epidermis of psoriasis patients, hBD-3 is likely to attenuate the development of psoriasis via IL-37 expression." (PMID 37834081, 2023). "In AD and psoriasis, there is an imbalance of the IL-33–IL-37 axis, and pathogenesis is likely to occur via increased IL-33 and decreased IL-37." (PMID 37834081, 2023). "The concentration of IL-37 in the serum of psoriasis patients is low compared with that in healthy controls." (PMID 37834081, 2023). "IL-33 and IL-37 are also deeply involved in the pathogenesis of inflammatory skin diseases such as atopic dermatitis (AD) and psoriasis." (PMID 37834081, 2023). "Here, we outline recent findings on the mechanisms regulating IL-33 and IL-37 expression in AD and psoriasis." (PMID 37834081, 2023).
psoriasis (continued). "The aim of this study was to examine the plasma concentrations of IL-36α, IL-36β, and IL-37 in psoriasis and their correlations with disease activity parameters." (PMID 36142901, 2022). "In this study, we examined the plasma concentrations of IL-36α, IL-36β, and IL-37 in patients with psoriasis." (PMID 36142901, 2022). "Accordingly, we have shown that tapinarof and GFF, which act on AHR, increased the expression of IL-37, which in turn suppressed the expression of IL-33, a crucial cytokine in the development of AD and psoriasis." (PMID 35663970, 2022). "In patients with psoriasis, we observed statistically significantly decreased plasma concentrations of IL-36β and IL-37." (PMID 36142901, 2022). "It has also been reported that IL-37 expression is markedly downregulated in biopsies from lesional psoriasis human skin compared with the level in paired samples of non-lesional skin." (PMID 35663970, 2022). "The concentrations of IL-37 were statistically significantly lower in patients with psoriasis in comparison with control subjects." (PMID 36142901, 2022). "According to our analysis, with the treatment of immunosuppressants in psoriasis, the expression of IL-37 increased gradually, while IL-19, CXCL1, CXCL2, CXCL13 decrease gradually." (PMID 36389813, 2022). "The aim of this study was to examine the plasma concentrations of IL-36α, IL-36β, and IL-37 in psoriasis and their correlation with disease activity parameters." (PMID 36142901, 2022). "The results of our study indicated increased plasma levels of IL36α and decreased plasma levels of IL-36β and IL-37 in patients with psoriasis." (PMID 36142901, 2022). "Several studies have examined the role of IL-36 and IL-37 in the pathogenesis of psoriasis; however, the influence of these cytokines on the clinical course of psoriasis is not fully understood." (PMID 36142901, 2022). "We believe that the AHR/IL-37 axis will be important for future therapeutic strategies for treating AD and psoriasis." (PMID 35663970, 2022). "In patients with psoriasis, we observed statistically significantly decreased plasma concentrations of IL-36β and IL-37, whereas plasma concentrations of IL-36α were increased." (PMID 36142901, 2022). "Previous studies suggest a role for IL-37 in the pathogenesis of psoriasis, but the findings are inconsistent." (PMID 36142901, 2022). "We found that the AHR-mediated IL-37 upregulation attenuates IL-33 expression which is one of the critical cytokines responsible for AD and psoriasis." (PMID 35663970, 2022). "One study further indicated that successful treatment of psoriasis patients with the Janus kinase (JAK) inhibitor tofacitinib restored IL37 expression levels in the skin." (PMID 33796114, 2021). "In this article, we confirm that IL-38 and IL-37 cytokines emerge as inhibitors of inflammation in psoriasis, and hold promise as an innovative therapeutic tool." (PMID 34360845, 2021). "In fact, this cytokine was found to be higher in some rheumatic diseases, including psoriasis, showing that the body produces IL-37 as a response to excessive inflammation." (PMID 34360845, 2021). "IL-37 is involved in the inflammatory process of a series of diseases, such as atherosclerosis, asthma, inflammatory bowel disease, psoriasis, rheumatoid arthritis, systemic lupus erythematosus, and ocular inflammatory diseases." (PMID 33381572, 2020). "The additional knowledge and treatment modalities will also prove to be advantageous for treating other diseases like psoriasis and rheumatoid arthritis due to cytokines like IL-37 and IL-17 also being heavily involved in this inflammatory process as well." (PMID 32968566, 2020). "The critical role of IL-37 in inhibiting skin inflammation has been identified and described in human and animal models of psoriasis." (PMID 30871134, 2019).
psoriasis (continued). "Here, we will provide a comprehensive and updated description of the molecular and biologic features of the IL-36, IL-37, and IL-38 agonists and antagonists, particularly in the context of psoriasis, PsA and RA." (PMID 30871134, 2019). "In this review, we will focus on the state of the art of the molecular features and biological roles of IL-36, IL-37, and IL-38 in representative skin- and joint-related inflammatory diseases, namely psoriasis, rheumatoid arthritis, and psoriatic arthritis." (PMID 30871134, 2019). "Nevertheless, overall elevations in IL-37 levels corroborate previous reports documenting elevation of IL-37 in relation to increasing amounts of inflammatory markers in chronic inflammatory processes such as psoriasis." (PMID 29641433, 2018). "In another previous study using RNA-seq for psoriasis samples the IL37 was found to be down-regulated in lesional skin." (PMID 25897967, 2015). "IL-37 expression was also significantly increased in the skin lesions of patients with psoriasis and in macrophages of Crohn's disease lesions." (PMID 25214710, 2014). "It is evident that the release of NETs is an important factor in the activation of pDCs and the early development of psoriasis, and the mechanism may involve IL37, NE, SLPI, and HBD‐2." (PMID 40060194, 2025). "Furthermore, the exogenous administration of IL-37 has been shown to attenuate psoriatic manifestations in the K14-VEGF-Tg humanized mouse model of psoriasis." (PMID 40731810, 2025). "The high expression of IL‐37 surrounding psoriatic plaque may contribute to the sharp demarcation of inflammatory morphology changes observed in psoriasis." (PMID 39157924, 2025). "However, our results indicate strong increased expression of IL‐37 around a psoriasis plaque in healthy‐looking skin compared with uninvolved skin sampled from different sites of the body." (PMID 39157924, 2025). "Furthermore, tofacitinib, a JAK inhibitor, was found to improve the skin lesions in psoriasis patients with an increase of the epidermal expression of IL-37." (PMID 37834081, 2023). "As we have shown, IL-33 and IL-37 are highly expressed in the epidermis of AD and psoriasis." (PMID 37834081, 2023). "In addition, the injection of a plasmid containing human IL-37 improved the skin lesions with reduced IFN-γ expression in a mouse model of psoriasis in which epidermis-specific VEGF-A was overexpressed." (PMID 37834081, 2023). "Based on these findings, IL-37 is expected to have potential to attenuate the development of various inflammatory diseases including inflammatory skin diseases such as atopic dermatitis (AD) and psoriasis through its anti-inflammatory effects." (PMID 35663970, 2022). "Both elevated and reduced IL-37 expression has been demonstrated in various forms of psoriasis." (PMID 36142901, 2022). "Furthermore, we found that the knockdown of IL-37 resulted in the upregulation of IL-33, an alarmin cytokine with crucial roles in the pathogenesis of AD and psoriasis." (PMID 35663970, 2022). "Although the precise role of IL-37 in the development of psoriasis remains unclear, intradermal injection of recombinant human IL-37 into a murine imiquimod-induced psoriasis model reportedly demonstrated a trend toward a protective effect." (PMID 35663970, 2022). "Additionally, we compared the plasma concentrations of IL-36α, IL-36β, and IL-37 between men and women with psoriasis." (PMID 36142901, 2022). "Taken together, our findings provide the first evidence that tapinarof and GFF could have potential to prevent IL-33-overexpressing disorders such as AD and psoriasis via the AHR/IL-37 axis." (PMID 35663970, 2022). "In this article we report that IL-38 and IL-37 may represent a new potential anti-inflammatory therapeutic pathway in psoriasis, and probably in other skin diseases mediated by IL-1 family members." (PMID 34360845, 2021).
psoriasis (continued). "IL-37 is a member of the IL-1 gene family that broadly inhibits inflammation in various inflammatory and autoimmune diseases, while also reducing acquired immunity, paving the way for the healing of psoriasis." (PMID 34360845, 2021). "Several authors report that IL-37 is involved in rheumatic diseases and psoriasis, and could certainly play a role in the treatment of these complex pathologies." (PMID 34360845, 2021). "Even if further studies are needed to clarify the divergent expression of IL-37 in the circulation and within the synovium, overall, these data suggest that IL-37 might be exploited not only to treat psoriasis but also RA." (PMID 30871134, 2019). "IL-37 has been shown to play immunoregulatory roles in animal models of myocardial infarction, RA, diabetes, fungal infection, septic shock, colitis, hepatitis, contact-hypersensitivity, psoriasis, and fibrosarcoma." (PMID 29988381, 2018). "Additionally, other studies suggest that IL-37 has anti-inflammatory effects on psoriasis." (PMID 36142901, 2022). "Therefore, an agent applied topically on the skin that can increase IL-37 could be promising for treating AD and psoriasis; however, the mechanism regulating IL-37 remains largely unknown." (PMID 35663970, 2022). "However, miR-155/GATA3/IL-37 may be an available option for psoriasis treatment, which requires additional clinical studies." (PMID 34025671, 2021). "Therefore, induction of IL-37 in keratinocytes by PG102 may be a novel approach to alleviate psoriasis." (PMID 30918469, 2019). "Thus, IL-37 may be an important immunoregulatory factor in the development of psoriasis and exert its effects by inhibiting the expression of key proinflammatory cytokines." (PMID 29805973, 2018). "In the skin, IL-37 has been shown to inhibit the expression of various pro-inflammatory mediators, including IL-6 and CXCL8, which are involved in the pathogenesis of psoriasis." (PMID 36142901, 2022). "Lastly, IL-37 is able to inhibit IL-1β, IL-6, TNF, and chemokines such as CCL2, all involved in psoriasis." (PMID 36012744, 2022). "Briefly, the miR-155/GATA3/IL-37 axis regulates the production of CXCL8 and IL-6 by stimulating TNF-α to affect the progression of psoriasis." (PMID 34025671, 2021). "In psoriasis, miR155 was also reported to regulate GATA3 downstream IL-37 mediated inflammatory responses." (PMID 34777377, 2021). "In our study, we observed reduced serum IL-37 levels in patients with psoriasis that did not correlate with disease activity parameters." (PMID 36142901, 2022). "To date, IL-37 has not been extensively studied in psoriasis patients, although its role in inhibiting skin inflammation has been confirmed in human and animal models of psoriasis." (PMID 36142901, 2022). "We did not detect differences in plasma concentrations of IL-36α, IL-36β, and IL-37 between men and women with psoriasis and smoking and non-smoking patients." (PMID 36142901, 2022). "The IL-37 localized on granular layer that is frequently absent in psoriasis, resulting decreased expression of IL-37 in lesion skin." (PMID 36389813, 2022). "IL-37 inhibits the IL-1β, IL-6, and TNF cytokines—which play fundamental roles in psoriatic inflammation—but it can also suppress some chemokines, such as CCL2, which is also important in psoriasis and rheumatic diseases." (PMID 34360845, 2021). "After silencing IL37, cells were stimulated with a mixture of five cytokines designated as M5 (IL-1α, IL-17A, IL-22, Oncostatin M, and TNF-α) to mimic the microenvironment of keratinocytes in psoriasis." (PMID 30918469, 2019). "Aberrant expression of IL-37 has been reported in autoimmune diseases, such systemic lupus erythematosus, rheumatoid arthritis, inflammatory bowel disease, and psoriasis; however, its role in MS has not yet been documented." (PMID 28842429, 2017). "IL37 (IL1F7) was up-regulated only in the non-lesional psoriatic skin, which makes its role in psoriasis very intriguing." (PMID 25897967, 2015).